PRB2 (proline rich protein BstNI subfamily 2)
Synonyms: PRPPRB1; Ps; cP7; IB-9
Tractability: Antibody: UniProt places it where antibodies can reach, with medium confidence; UniProt predicts a signal peptide or a membrane-spanning region; its Gene Ontology location is reachable by antibodies, with medium confidence.
Gene: Protein-coding gene on chromosome 12 (11,391,540 to 11,501,041, reverse strand). Ensembl gene ENSG00000121335.
Subcellular location: Secreted
Gene Ontology:
Molecular function: protein binding
Cellular component: extracellular region
Genetic constraint (gnomAD): Loss-of-function variants: 12 observed, 8.4 expected, observed/expected ratio (o/e) 1.43, 90% interval 0.89 to 1.91. That is too few expected variants to judge how well the gene tolerates losing a copy. Missense variants: 447 observed, 385.61 expected, observed/expected ratio (o/e) 1.16, 90% interval 1.07 to 1.25. Synonymous variants: 139 observed, 136.67 expected, observed/expected ratio (o/e) 1.02, 90% interval 0.88 to 1.17.
Homologues: Paralogues in human: PRB3 (63% identical), PRB4 (45% identical), PRB1 (39% identical), PRH1 (28% identical), PRH2 (25% identical), PRR4 (12% identical).
Diseases named in the same sentence as PRB2 in open-access papers:
PRB2 is named in the same sentence as 39 diseases in open-access papers, as found by Europe PMC text mining. Sharing a sentence is not in itself a finding about the gene and the disease. The quoted sentences say what the papers report.
breast cancer (6 papers, 2010 to 2021). A primary or metastatic malignant neoplasm involving the breast. "For example, the HCN4 gene is highly correlated with lower survival rates of breast cancer, and the gene PRB2 is significantly related to prognosis as an independent prognostic marker." (PMID 33537063, 2020). "In addition, the same laboratory demonstrated that 5′-Aza-2′-deoxycytidine reorganization of pRB2/DNMT1 multimeric complex on ERα gene promoter and modulated its expression in breast cancer cell lines." (PMID 33604794, 2021). "A recent study has shown that a multimolecular complex, pRb2/p130-E2F4/5-HDAC1-DNMT1-SUV39H1, binding to the ERα promoter, is associated with ERα transcriptional repression in ERα-negative breast cancer MDA-MB-231 cells." (PMID 20946668, 2010).
Burkitt lymphoma (1 paper, 2009). A rare form of malignant mature B-cell non-Hodgkin lymphoma. "We have shown that endemic Burkitt lymphoma from Uganda tend to express pRb2, a cell cycle protein associated with growth arrest, although intense cell proliferation is a characteristic feature of this cancer type." (PMID 19691827, 2009). "In the present study, we have analyzed pRb2 expression and searched for RBL2 mutations in endemic Burkitt lymphoma from Uganda." (PMID 19691827, 2009). "Nearly all of our cases (84.0%) were positive for pRb2 protein expression although this protein is a marker for growth arrest and Burkitt lymphoma is characterized by a high proliferation rate." (PMID 19691827, 2009). "However, altered subcellular localization of pRb2 and mutations in the pRb2-encoding gene RBL2 have been described for some tumours, including Burkitt lymphomas (BL)." (PMID 19691827, 2009).
Cognitive impairment (1 paper, 2024). Abnormal cognition is characterized by deficits in thinking, reasoning, or remembering. "The significance of the associations between cognitive impairment and increased expression levels of DLX6 and PRB2 was marginally below the threshold (z-score = 3.582; p-value = 3.41 × 10−4PRB2; z-score = 3.699; p-value = 2.17 × 10−4, respectively)." (PMID 38542318, 2024).
lymphoid tumour (1 paper, 2009). "Normal human lymphocytes and osteosarcoma cell lines exhibited exclusive nuclear pRb2 localization whereas lymphoid tumour cell lines were noted to express the protein in the cytoplasm." (PMID 19691827, 2009). "The proportion of tumours with absent pRb2 expression (16.0%) in our series is comparable to what has been reported in non-lymphoid tumours." (PMID 19691827, 2009).
lymphoma (1 paper, 2009). A malignant (clonal) proliferation of B- lymphocytes or T- lymphocytes which involves the lymph nodes, bone marrow and/or extranodal sites. "This might also explain the observation that pRb2 expression is elevated in AIDS-related lymphomas, although the fundamental differences between HIV and Epstein-Barr virus should be kept in mind." (PMID 19691827, 2009).
non-Hodgkin lymphoma (1 paper, 2009). Distinct from Hodgkin lymphoma both morphologically and biologically, non-Hodgkin lymphoma (NHL) is characterized by the absence of Reed-Sternberg cells, can occur at any age, and usually presents as a localized or generalized lymphadenopathy associated with fever and weight loss. "In a series of untreated patients with non-Hodgkin's lymphoma (various types), low levels of pRb2 were reported to correlate with high levels of p107 and proliferation-associated proteins." (PMID 19691827, 2009). "Expression of pRb2 has been demonstrated in a variety of normal tissues and tumours, for example in hematopoietic and epithelial cells, atypical endometrial hyperplasia and carcinoma and non-Hodgkin lymphomas." (PMID 19691827, 2009).
ovarian carcinoma (1 paper, 2020). A malignant neoplasm originating from the surface ovarian epithelium. "Our findings indicate a clear role of pRb2/p130 protein in the tumor progression of intestinal-type mucinous BOTs thus suggesting a possible role of Rb proteins as prognostic factors in ovarian cancer." (PMID 33262995, 2020).
prostate carcinoma (1 paper, 2021). A carcinoma that arises from epithelial cells of the prostate gland. "Inositol hexaphosphate (IP6) inhibits growth, and induces G1 arrest and apoptotic death of prostate carcinoma DU145 cells via decreasing the level of E2F4 as well as via increasing binding of E2F4 with pRb/p107 and pRb2/p130, thus modulating CDKI-CDK-cyclin and pRb-related protein-E2F complexes." (PMID 33390186, 2021).
tumor (10 papers, 2009 to 2024). "In fact, loss of pRb2/p130 expression has been previously reported to inversely correlate with tumor grade and to be a poor prognostic indicator in several human cancers." (PMID 33262995, 2020). "The overexpression of pRb2/p130 not only suppresses tumor formation in nude mice, but also causes the regression of established tumor grafts, suggesting that pRb2/p130 modulates the angiogenetic balance." (PMID 24658119, 2014). "The aim of this study was to investigate pRb2 expression in endemic BL cases from Uganda and to search for tumour-associated, somatic RBL2 mutations that could be involved in deregulated cell cycle control." (PMID 19691827, 2009). "HCV core appears indeed able to significantly down-regulate the expression and the function of two out of three RB family tumor and growth suppressor factors, i.e. pRb and pRb2/p130." (PMID 26576645, 2015). "The cytoplasmic localization of pRb2 in BL tumour tissue and in lymphoid cell lines has been attributed to mutations which lead to disruption of the NLS." (PMID 19691827, 2009). "PRB2, a tumor suppressor, a premature stop codon was identified in our study, suggesting that its down-regulation and dysfunction might occur in patients." (PMID 33680914, 2020). "With the aim of identifying novel molecular mechanisms of hepatocyte transformation by HCV, we examined the effect of HCV core protein on the expression of the whole Retinoblastoma (RB) family of tumor and growth suppressor factors, i.e. pRb, p107 and pRb2/p130." (PMID 26576645, 2015). "The majority of tumours in our series (84.0%) were positive for pRb2 expression." (PMID 19691827, 2009). "Moreover, loss of this protein may not be sufficient to deregulate the orderly progression of the cell cycle, as mice unable to express pRb2 do not exhibit any altered tumour predisposition or developmental defects." (PMID 19691827, 2009). "Our findings suggest that both pRb and pRb2/p130 do not play a key role in the tumor progression of serous borderline tumors since these proteins remain located in the nucleus and never showed cytoplasmic localization." (PMID 33262995, 2020). "It remains to be investigated whether BLs negative for pRb2 constitute a subset of tumours with specific biological properties affecting for example patient survival." (PMID 19691827, 2009).
cancer (6 papers, 2009 to 2020). A tumor composed of atypical neoplastic, often pleomorphic cells that invade other tissues. "The role of pRb2 in cancer development is, however, still debatable." (PMID 19691827, 2009). "Whereas disturbed function of pRb is commonly seen in human cancers, it is still an open question whether pRb2 is involved in tumorigenic processes." (PMID 19691827, 2009).
PRB2 also shares sentences with these, for which no sentence is quoted: thrombophilia (10 papers); venous thromboembolism (4); familial Alzheimer disease (2); ischemic stroke (2); melanoma (2); thrombosis (2); AIDS (1); amyloidosis (1); antithrombin deficiency (1); atherosclerosis (1); coagulation disorder (1); cyst (1); dengue (1); diabetes mellitus (1); glioma (1); hepatocellular carcinoma (1); hereditary thrombophilia (1); infection (1); Iron deficiency anemia (1); lymph node metastasis (1); mucinous ovarian tumor (1); myeloproliferative neoplasm (1); Obesity (1); osteosarcoma (1); pulmonary embolism (1); Purpura Fulminans (1); Thrombocytopenia (1); varicella (1); viral infection (1).